KCND2 (potassium voltage-gated channel subfamily D member 2)
Description:
Voltage-gated potassium channel that mediates transmembrane potassium transport in excitable membranes, primarily in the brain. Mediates the major part of the dendritic A-type current I(SA) in brain neurons (By similarity). This current is activated at membrane potentials that are below the threshold for action potentials. It regulates neuronal excitability, prolongs the latency before the first spike in a series of action potentials, regulates the frequency of repetitive action potential firing, shortens the duration of action potentials and regulates the back-propagation of action potentials from the neuronal cell body to the dendrites. Contributes to the regulation of the circadian rhythm of action potential firing in suprachiasmatic nucleus neurons, which regulates the circadian rhythm of locomotor activity (By similarity). Functions downstream of the metabotropic glutamate receptor GRM5 and plays a role in neuronal excitability and in nociception mediated by activation of GRM5 (By similarity). Mediates the transient outward current I(to) in rodent heart left ventricle apex cells, but not in human heart, where this current is mediated by another family member. Forms tetrameric potassium-selective channels through which potassium ions pass in accordance with their electrochemical gradient. The channel alternates between opened and closed conformations in response to the voltage difference across the membrane. Can form functional homotetrameric channels and heterotetrameric channels that contain variable proportions of KCND2 and KCND3; channel properties depend on the type of pore-forming alpha subunits that are part of the channel. In vivo, membranes probably contain a mixture of heteromeric potassium channel complexes. Interaction with specific isoforms of the regulatory subunits KCNIP1, KCNIP2, KCNIP3 or KCNIP4 strongly increases expression at the cell surface and thereby increases channel activity; it modulates the kinetics of channel activation and inactivation, shifts the threshold for channel activation to more negative voltage values, shifts the threshold for inactivation to less negative voltages and accelerates recovery after inactivation. Likewise, interaction with DPP6 or DPP10 promotes expression at the cell membrane and regulates both channel characteristics and activity (By similarity). Upon depolarization, the channel goes from a resting closed state (C state) to an activated but non-conducting state (C* state), from there, the channel may either inactivate (I state) or open (O state).
Synonyms: KIAA1044; Kv4.2; RK5
Tractability: Small molecule: an approved drug acts on it; it belongs to a druggable protein family. Antibody: UniProt places it where antibodies can reach, with high confidence; its Gene Ontology location is reachable by antibodies, with high confidence; UniProt predicts a signal peptide or a membrane-spanning region. PROTAC: its protein half-life has been measured.
Target class: Potassium channels; Ion channel; Voltage-gated ion channel; Voltage-gated potassium channel
Gene: Protein-coding gene on chromosome 7 (120,273,175 to 120,750,337, forward strand). Ensembl gene ENSG00000184408.
Subcellular location: Cell membrane; Cell projection, dendrite; Synapse; Perikaryon; Postsynaptic cell membrane; Cell projection, dendritic spine; Cell junction
Pathways (Reactome):
Muscle contraction: Phase 1 - inactivation of fast Na+ channels
Neuronal System: Voltage gated Potassium channels
Gene Ontology:
Molecular function: A-type (transient outward) potassium channel activity; protein binding; voltage-gated potassium channel activity; voltage-gated monoatomic ion channel activity involved in regulation of postsynaptic membrane potential; monoatomic ion channel activity
Biological process: action potential; membrane repolarization; muscle contraction; potassium ion transmembrane transport; cellular response to hypoxia; chemical synaptic transmission; regulation of heart contraction; locomotor rhythm; monoatomic ion transport; neuronal action potential; potassium ion transport; protein homooligomerization; regulation of postsynaptic membrane potential; sensory perception of pain; transmembrane transport
Cellular component: Kv4.2-KChIP2 channel complex; plasma membrane; voltage-gated potassium channel complex; anchoring junction; dendritic spine; neuronal cell body; neuronal cell body membrane; perikaryon; plasma membrane raft; postsynaptic membrane; synapse; dendrite; GABA-ergic synapse; glutamatergic synapse; membrane; postsynaptic specialization membrane
Genetic constraint (gnomAD): Loss-of-function variants: 14 observed, 51.12 expected, observed/expected ratio (o/e) 0.27, 90% interval 0.18 to 0.43. The upper end of that interval is the gene's LOEUF score, 0.43, which puts it in group 1 of 6, group 1 being the genes least tolerant of losing a copy. Missense variants: 476 observed, 847.16 expected, observed/expected ratio (o/e) 0.56, 90% interval 0.52 to 0.61. Synonymous variants: 317 observed, 323.22 expected, observed/expected ratio (o/e) 0.98, 90% interval 0.89 to 1.08.
Gene-disease validity (ClinGen):
ClinGen rates the evidence that KCND2 causes each of these diseases.
KCND2-related neurodevelopmental disorder with or without seizures (autosomal dominant): Moderate. A neurodevelopmental disorder caused by variation in the KCND2 gene.
Homologues: Orthologues: chimpanzee KCND2 (100% identical), macaque KCND2 (99% identical), guinea pig KCND2 (99% identical), pig KCND2 (99% identical), rat Kcnd2 (99% identical), mouse Kcnd2 (99% identical), rabbit KCND2 (99% identical), dog KCND2 (98% identical), tropical clawed frog kcnd2 (84% identical), zebrafish kcnd2 (80% identical). Paralogues in human: KCND3 (77% identical), KCND1 (67% identical), KCNB2 (30% identical), KCNA2 (27% identical), KCNA3 (27% identical), KCNA4 (27% identical), KCNA1 (26% identical), KCNA5 (26% identical), KCNC1 (26% identical), KCNC3 (26% identical), KCNC4 (26% identical), and 19 more.